CCDC70 (coiled-coil domain containing 70)
Synonyms: DKFZP434K1172; FLJ25853
Tractability: Antibody: its Gene Ontology location is reachable by antibodies, with medium confidence.
Gene: Protein-coding gene on chromosome 13 (51,861,969 to 51,866,232, forward strand). Ensembl gene ENSG00000123171.
Gene Ontology:
Molecular function: protein binding
Cellular component: plasma membrane
Genetic constraint (gnomAD): Loss-of-function variants: 10 observed, 13.81 expected, observed/expected ratio (o/e) 0.72, 90% interval 0.45 to 1.23. The upper end of that interval is the gene's LOEUF score, 1.23, which puts it in group 5 of 6, group 1 being the genes least tolerant of losing a copy. Missense variants: 308 observed, 286.16 expected, observed/expected ratio (o/e) 1.08, 90% interval 0.98 to 1.18. Synonymous variants: 119 observed, 99.19 expected, observed/expected ratio (o/e) 1.2, 90% interval 1.03 to 1.4.
Homologues: Orthologues: chimpanzee CCDC70 (99% identical), macaque CCDC70 (93% identical), pig CCDC70 (84% identical), mouse Ccdc70 (83% identical), rabbit CCDC70 (82% identical), rat Ccdc70 (81% identical), dog CCDC70 (80% identical). Paralogues in human: CBY2 (23% identical), CBY3 (9% identical), CBY1 (8% identical).
Diseases named in the same sentence as CCDC70 in open-access papers:
CCDC70 is named in the same sentence as 1 disease in open-access papers, as found by Europe PMC text mining. Sharing a sentence is not in itself a finding about the gene and the disease.
CCDC70 shares sentences with these, for which no sentence is quoted: tumor (1 paper).